HGF (hepatocyte growth factor)
Diseases named in the same sentence as HGF in open-access papers (continued):
Sharing a sentence is not in itself a finding about the gene and the disease.
cancer (continued). "Here, live PANC-1, SW620, and MCF7 cancer cells were added to TGFβ-1 (4.0 × 10−3 μg/mL), IL-6 (4.1 × 10−5 μg/mL), HGF (5.97 × 10−4 μg/mL), or untreated together with sialidase substrate 4-MUNANA (emission 450 nm, excitation 365 nm) for 1 min." (PMID 40227834, 2025). "Here, we investigated the metabolic activity of PANC-1, SW620, and MCF-7 cancer cells following treatment with TGFβ-1, IL-6, and HGF at predetermined concentrations." (PMID 40227834, 2025). "Impaired TGFβ signaling, caused by reduced TGFBR2 expression in CAFs, leads to increased secretion of HGF, further contributing to cancer progression (TGFB-HGF axis)." (PMID 40075643, 2025). "As a result, the HGF/c-MET pathway has emerged as a significant therapeutic target in various cancers." (PMID 40520181, 2025). "MET and its ligand, hepatocyte growth factor (HGF), are observed in most solid tumors, and signaling via MET is known to be associated with a number of malignant tumors." (PMID 40004241, 2025). "The mRNA expression of cancer-related molecules, including those within the HGF/MET signaling pathway, were determined by microarray analysis, and compared between non-metastatic CRTC2 and metastatic CRTC2 (liver metastasis: CRTC2-LV)." (PMID 40076928, 2025). "The use of inhibitors of the activation of the HGF/SF pathway counteracted the effects of XP fibroblasts on the growth of cancer cells, suggesting new perspectives in the care of XP patients." (PMID 39409898, 2024). "The HGF/c-MET pathway serves a critical role in cancer and is an attractive therapeutic target for cancer therapy." (PMID 38763973, 2024). "In the cancer cohort (N = 65), low circulating HGF (P = 0.023, P = 0.029), low IL-6 (P = 0.002, P < 0.001), and high CCR (P = 0.031, P = 0.008) were associated with significantly improved progression-free survival (PFS) and overall survival (OS)." (PMID 38776028, 2024). "HGF stimulation promotes the Warburg effect and glutamine breakdown, thereby promoting the biogenesis of multiple cancer cells." (PMID 38318160, 2024). "Human cancer development has been linked to the tyrosine kinase receptor MET, which is encoded by the MET gene to interact with the hepatocyte growth factor (HGF) to activate downstream pathways and promote cell proliferation, migration, and angiogenesis." (PMID 38893154, 2024). "Fibroblast-derived hepatocyte growth factor (HGF) activates Wnt/β-catenin signalling and subsequently clonogenicity in cancer stem cells isolated from CRC patients and then promotes the development of CRC." (PMID 38519641, 2024). "PSCs also advance cancer by synthesizing molecules like galectin-1, hepatocyte growth factor (HGF), stromal cell-derived factor-1 (SDF-1), IL-6, and TGFβ." (PMID 39199647, 2024). "Cancer-associated fibroblasts (CAFs) are key producers of HGF, which signals to MET-expressing cancer cells, promoting their growth." (PMID 39598385, 2024). "By activating MET kinase, which directly affects mitochondrial fission HGF (hepatocyte growth factor) plays a crucial role in the migration and invasion of cancer cells in the HCC microenvironment." (PMID 39463763, 2024). "Paracrine secretion of HGF in turn mediates the interaction with migrated cancer cells via binding c-Met, thereby establishing the GC metastatic niche." (PMID 38339318, 2024). "Cytokine array analysis of malignant ascites showed that IL-6 and, to a lesser extent, the hepatocyte growth factor (HGF) were enriched in OC ascites." (PMID 39001541, 2024). "At the initial stages of malignancy, fibroblasts can secrete TGFβ and hepatocyte growth factor, inducing the initiation of cancer within the normal human epithelium." (PMID 39033778, 2024). "Hepatocyte growth factor (HGF)/c-Met pathway plays a pivotal role in cancer invasion and metastasis, and its overexpression has been associated with colorectal liver metastasis." (PMID 39167197, 2024).
cancer (continued). "HGF-neutralizing antibodies are potential therapeutic tools in disrupting this cross-communication signal between stromal and cancer cells." (PMID 39598385, 2024). "These advancements underscore the diverse strategies and promising outcomes in addressing cancer through targeting the HGF/c-MET pathway." (PMID 39664377, 2024). "It was found that HGF/c-MET signaling activated the RAS/RAF pathway, down-regulated cancer cell apoptosis, and was associated with the overexpression of cytoprotective HO-1 and anti-apoptotic Bcl-2/Bcl-xL." (PMID 39664377, 2024). "Aberrant MET/HGF regulation is observed in a wide variety of human cancers with a dysregulated proliferative and invasive signaling program, epithelial-to-mesenchymal transition, cell motility/migration, angiogenesis, invasion, and metastasis." (PMID 39087020, 2024). "Cross-talk between the liver macrophage subpopulation of SAMs and CAFs through WNT5 and hepatocyte growth factor (HGF) has been found to promote cancer and metastasis." (PMID 38730724, 2024). "This is likely due to the formation of protein complexes with c-Met and Hepatocyte Growth Factor, which reduce CD44v6 endocytic performance while activating a signalling pathway leading to cancer invasiveness and metastatic spread." (PMID 38600583, 2024). "Here, we chose MET, a tyrosine kinase receptor of HGF, as a treatment target because various cancers, including OC, are characterized by an alternating MET expression, which is generally associated with a poor prognosis and aggressive phenotypes." (PMID 38672564, 2024). "In this table, recording the MET mutations characterized by functional studies, subdomain localization of MET mutations were indicated as well as their sensitivity to hepatocyte growth factor (HGF) stimulation and the cancer type in which they were identified." (PMID 38652103, 2024). "MET and its ligand, HGF, participate in signaling pathways involved in oncogenic processes, including cell proliferation regulation, invasion, angiogenesis, and cancer stem cell regulation." (PMID 39519229, 2024). "Abnormal HGF/MET signaling is implicated in the development and metastasis of various malignant tumors, including sarcomas." (PMID 38596618, 2024). "Zhang haiyang found that hepatocyte growth factor (HGF) siRNA packaged in exosomes can be transported into cancer cells, significantly downregulating the expression of HGF to inhibit the proliferation and migration of cancer and vascular cells." (PMID 39703839, 2024). "The data demonstrated that cancer growth, proliferation, and HGF-related pathways were significantly suppressed in the Met-siExosome group compared to the control group." (PMID 38672564, 2024). "We demonstrated that DA exerted anti-cancer activities by targeting HGF/c-Met signaling in the HCC model." (PMID 37835375, 2023). "Hepatocyte growth factor (HGF): HGF is a protein related to the main hallmarks of cancer, participating in proliferation, migration, angiogenesis and drug resistance." (PMID 37760400, 2023). "Previous studies have indicated that inhibiting the BET domain attenuated cancer progression by mitigating PD-L1 expression and HGF-MET signaling." (PMID 36768307, 2023). "The MET receptor tyrosine kinase is known to activate various cellular functions that are crucial to organ development and cancer progression upon binding with its ligand, hepatocyte growth factor (HGF)." (PMID 37445965, 2023). "Previous studies have reported that HGF prevents apoptosis in both normal and cancer cells induced by various stimuli." (PMID 36761981, 2023). "Although there is variation between different patient groups, each cancer type demonstrated a similar postoperative trend for HGF." (PMID 38067195, 2023). "It is also possible that HGF detected in the cancer cells is produced in the stroma but bound on MET at the plasma membrane or in the cytoplasm after internalisation." (PMID 36799689, 2023).
cancer (continued). "In in vitro studies, the co-stimulation of EGF and HGF (hepatocyte growth factor) showed a synergistic effect on cell proliferation in cancer cells expressing both MET and EGFR (epidermal growth factor receptor)." (PMID 38137393, 2023). "Due to its multifunctional role in oncogenesis and cancer progression, the HGF–c-Met axis has recently been studied extensively in cancer research." (PMID 38089883, 2023). "When secreted into the TME, HGF binds to the MET receptor on the cancer cells and overcomes the inhibitory effect of receptor tyrosine kinase inhibitors (TKIs), such as sunitinib." (PMID 36761981, 2023). "In the microenvironment, it was reported that the major sources of HGF, amphiregulin, IGF‐1, and FGF‐2 are fibroblasts, leukocyte populations, cancer‐associated fibroblasts, and epithelial/endothelial cells, respectively." (PMID 36416133, 2023). "The elevated levels of lactate educate CAFs to secrete higher levels of HGF via an NF-κB-dependent mechanism that subsequently leads to cancer cell resistance against TKI therapy." (PMID 37065872, 2023). "Other cancer-related genes, such as HGF (encoding hepatocyte growth factor), FASP (encoding fibroblast-associated protein), and ACTA2 (encoding alpha smooth muscle actin 2) were highly expressed in CD90+ cells." (PMID 36747131, 2023). "Since few data on SCLC is avaliable from on-line database, we explore the expression of HGF in pan-cancer and analyzed its potential predictive value." (PMID 37828456, 2023). "As the hepatocyte growth factor (HGF) has been known to stimulate both cancer cell and vascular cell growth, the HGF-cMET pathway emerged as a viable target for clinical interventions." (PMID 37762393, 2023). "Cancer stem cells (CSCs) can produce inducers of HGF, including IL-1β, PDGF, TNF-α, bFGF, and prostaglandin E2 (PGE2)." (PMID 37919751, 2023). "These include epidermal growth factor (EGF), fibroblast growth factor (FGF), vascular endothelial growth factor (VEGF), and hepatocyte growth factor (HGF), each of which has been implicated in the malignant progression of various cancer types." (PMID 38067195, 2023). "This experimental model allows to correctly evaluate the contribution of the HGF/MET axis activation to the dissemination of human cancer cells." (PMID 37345079, 2023). "High HGF expression in cancer tissue or serum was found to correlate with advanced cancer stage and poor outcome." (PMID 35953652, 2023). "In two thirds of the patient samples with interpretable HGF immunostaining, expression was detected at the surface or cytoplasm of cancer cells, in addition to the classical stromal localisation." (PMID 36799689, 2023). "All together, these results strongly suggest that, HGF‐activated METex14 triggers in response to its ligand, important changes that can contribute to its oncogenicity during cancer progression." (PMID 36799689, 2023). "HGF exists in various tissues as a biologically inactive single‐chain polypeptide (scHGF) and is converted to functionally active two‐chain HGF (tcHGF) in the cancer microenvironment." (PMID 36416133, 2023). "LYZ is associated with neutrophil degranulation and host defense peptides, whereas COL1A1, COL1A2 along with HGF, TNC, and VEGFA are all part of the PI3K pathway, which plays an important role in cancer progression, and has been implicated in TNT regulation." (PMID 37955637, 2023). "In line with our observations, the accumulation of CAFs leads to a poor prognosis in CRC, and CAFs secrete molecules, such as HGF, that induce the aggressive, stem-like phenotype of cancer cells." (PMID 37511344, 2023). "The interesting finding is that, when cancer cells are exposed to CM from treated fibroblasts, the release of HGF is strongly prevented and, coherently, the activation of c-Met kinase is reduced." (PMID 37686233, 2023).
cancer (continued). "The biological behavior of cancer cells to generate EMT will be regulated by a large number of growth factors and cytokines including TGF-β, IL-6, EGF, VEGF and HGF, secreted from Cancer-associated fibroblasts (CAFs)." (PMID 37880742, 2023). "With the advancement of cancer treatment exploration, the HGF/c-MET axis has emerged as a significant target." (PMID 37919751, 2023). "HGF, a factor derived from fibroblasts, plays a role in facilitating the aggressive invasion of cancer cells." (PMID 37835402, 2023). "Collectively, these data show that the higher secretion of HGF by CD142high fibroblasts is involved in the differential cancer stimulating effect of these two fibroblast populations." (PMID 37511344, 2023). "When MACC1 was first associated with colorectal cancer, it was discovered that the HGF/c-Met signaling pathway played a role in its ability to promote cancer." (PMID 36979146, 2023). "A synthetic analog of chrysin named 8-bromo-7-methoxy chrysin inhibits the activation of hepatic stellate cells to CAFs, thereby reducing the stemness of cancer cells by impeding IL-6 and HGF signaling." (PMID 37065872, 2023). "In vitro studies showing that EGCG suppresses HGF and VEGF synthesis in cancer-associated fibroblasts supported the decrease in serum HGF and VEGF." (PMID 37110140, 2023). "Several evidences have shown that HGF/Met signaling is substantial in cancer cells for the maintenance of self-renewal mechanisms and even development of chemoresistance." (PMID 37170275, 2023). "One of the key mediators of PSC - cancer cell interactions is the hepatocyte growth factor (HGF)/c-MET pathway." (PMID 37354984, 2023). "The HGF/c-Met (Hepatocyte Growth Factor/Hepatocyte Growth Factor Receptor) signaling pathway is frequently reactivated by cancer cells during tumorigenesis, invasive growth, and metastatic progression." (PMID 38136231, 2023). "Hepatocyte growth factor (HGF)/Met receptor pathway signaling is frequently involved in cancer and is widely targeted in drug development." (PMID 36672409, 2023). "Circulating PD-L1, HGF, and MUC-16 have been associated with poor survival in BTC and other cancers, but all previous studies on BTC included less than 250 patients and lacked independent validation cohorts." (PMID 36831406, 2023). "The overlapping genes included five known cancer driver genes (including HGF, MET, and PIK3R1) and five putative FOXP2 targets, such as MET and PIK3R1, identified by chromatin immunoprecipitation assays in both mice and humans." (PMID 37668356, 2023). "Activation of bypass signaling mediated by the HGF‐MET pathway has been well recognized as a mechanism of resistance to targeted drugs in various cancers." (PMID 36416133, 2023). "Several clinical studies have addressed the role of the HGF/MET pathway in diverse types of cancer, such as gastric, colorectal, breast, hepatocellular, pancreatic, lung and renal cancer." (PMID 37170275, 2023). "MET is a receptor for hepatocyte growth factor, which is involved in the growth, invasion and metastasis of malignant tumours." (PMID 37445733, 2023). "All the studies reported to date have emphasized the prominent oncogenic role of the HGF/c-Met axis in human cancers." (PMID 37835375, 2023). "In this study, we applied CRISPR-Cas9 mediated knocking-out of the MET gene in cancer cells to cast light on the role played by the HGF/MET axis as a key regulator of cell-autonomous metastatic properties." (PMID 37345079, 2023). "Preclinical studies showed that MET blockade was effective only in those tumors harboring MET genomic alterations, while targeting the HGF/MET pathway in tumors with wild type MET had a poor effect on cancer cell proliferation." (PMID 37373267, 2023). "The regulation of the HGF expression between various types of cancer and normal tissues was investigated from the GTEx database and TCGA." (PMID 37828456, 2023).
cancer (continued). "Some cytokines secreted by CAFs, such as CXCL5, TGF-β, hepatocyte growth factor(HGF), and pro-angiogenic factors, play an important role in promoting malignant transformation and the proliferation and invasion of cancer cells." (PMID 36759842, 2023). "Despite promising pre-clinical evidence regarding the HGF/MET pathway in numerous solid types of cancer, results in our study show a surprisingly low clinical impact of HGF expression in chRCC." (PMID 37170275, 2023). "Of interest, microarray analysis showed that the expression of HGF, a potent growth-stimulating factor for cancer cells 41, is substantially up-regulated in the DRGs tibial injected with IP-B12." (PMID 37461623, 2023). "The HGF/MET axis was reported as a potential key contributor to promoting chemoresistance in cancer cells." (PMID 37175439, 2023). "Dysregulation of MET signaling has been found in a variety of cancers through different mechanisms, such as activating point mutations of the MET gene, overexpression of the ligand HGF, MET gene copy number gain (MET-CNG)/amplification, and MET gene fusions." (PMID 36765572, 2023). "In NSCLC, hepatocyte growth factor (HGF) and its receptor, c-Met, are mutationally upregulated, causing increased cancer cell growth, survival, and invasion." (PMID 37550007, 2023). "For instance, hepatocyte growth factor (HGF) is a cytokine being actively involved in the orchestrated crosstalk among different signalling pathways in cancer cells and exhibits a capability of regulating BMP and BMP receptors in cancer cells." (PMID 37333824, 2023). "For instance, taxifolin inhibits the stimulation of cancer cells by HGF secreted by adipocytes and does so by preventing activation of the SOS1-Grb2-CCL2 pathway." (PMID 36670988, 2023). "Neutrophils also play a role in promoting cancer growth by releasing growth factors, including epidermal growth factor, hepatocyte growth factor (HGF), and platelet-derived growth factor." (PMID 37894307, 2023). "Metastasis-Associated in Colon Cancer 1 (MACC1), a newly identified oncogene and regulator of the HGF/Met signaling pathway, has been shown to play a critical role in the development and progression of several types of cancer." (PMID 38021160, 2023). "HGF from TME has been shown to regulate the innate resistance of BRAF-mutant cancer cells to RAF inhibitors by activating the MAPK and PI3K/Akt signaling pathways in cancer cells." (PMID 37853413, 2023). "Aberrations in the HGF/MET pathway act as diagnostic, predictive, and prognostic biomarkers for cancers." (PMID 38022627, 2023). "The hepatocyte growth factor (HGF)/Met receptor pathway signaling is frequently involved in cancer and has been a subject of targeted drug development for nearly 30 years." (PMID 36672409, 2023). "Plasma growth factor levels were analyzed in surgical cancer patients, including hepatocyte growth factor (HGF), epidermal growth factor (EGF), and insulin-like growth factor-1 (IGF-1)." (PMID 38067195, 2023). "The HGF/c-Met signaling pathway, frequently reactivated in cancer progression, plays a central role in tumorigenesis, invasive growth, and metastatic advancement." (PMID 38136231, 2023). "The MET receptor with its ligand HGF synchronizes a range of functions of cells, where many cellular functions can be disturbed in human cancers." (PMID 37200850, 2023). "The observed net MET and HGF mRNA levels are the sum of reduction by foretinib and induction by natural cancer disease progression." (PMID 36614199, 2023). "The Cancer cell growth, survival, and migration of cancer cell are relied on an HGF-dependent manner." (PMID 37293508, 2023). "Secreted inflammatory cytokines in cancer cells, including IL-22, IL-6, IL-8, IL-4, IL-1β, HGF, IGF-1, EGF, G-CSF, TNF-α, VEGF, and IL-11, can confer the promotion of chemo- and radioresistance." (PMID 38140352, 2023).